TSACC (TSSK6 activating cochaperone)
Description:
Co-chaperone that facilitates HSP-mediated activation of TSSK6.
Synonyms: SIP; SSTK-IP; C1orf182
Tractability: No criterion of Open Targets' tractability assessment is met for any kind of drug.
Gene: Protein-coding gene on chromosome 1 (156,337,314 to 156,346,995, forward strand). Ensembl gene ENSG00000163467.
Subcellular location (Human Protein Atlas): Nuclear bodies; Nucleoplasm
Gene Ontology:
Molecular function: protein binding; protein-folding chaperone binding
Cellular component: cytoplasm
Genetic constraint (gnomAD): Loss-of-function variants: 5 observed, 10.41 expected, observed/expected ratio (o/e) 0.48, 90% interval 0.25 to 1.01. The upper end of that interval is the gene's LOEUF score, 1.01, which puts it in group 4 of 6, group 1 being the genes least tolerant of losing a copy. Missense variants: 137 observed, 151.67 expected, observed/expected ratio (o/e) 0.9, 90% interval 0.79 to 1.04. Synonymous variants: 54 observed, 58.62 expected, observed/expected ratio (o/e) 0.92, 90% interval 0.74 to 1.16.
Homologues: Orthologues: macaque TSACC (98% identical), pig TSACC (82% identical), rabbit TSACC (73% identical), rat Tsacc (71% identical), mouse Tsacc (63% identical).
Diseases named in the same sentence as TSACC in open-access papers:
TSACC is named in the same sentence as 4 diseases in open-access papers, as found by Europe PMC text mining. Sharing a sentence is not in itself a finding about the gene and the disease. The quoted sentences say what the papers report.
Infertility (1 paper, 2019). "These genes play important roles in cell proliferation (RFX4, FOXM1, ASF1B), differentiation during spermatogenesis (CATSPERG, SPDYA, SPATA16, TSACC, TCP10L, DPY19L2) and motility of sperm cells during fertilization (DNAAF1); mutations in these genes may lead to infertility." (PMID 31671693, 2019).
oligospermia (1 paper, 2017). Decreased number of spermatozoa in the semen. "Eight genes among 817 genes (0.01%) (ADAM32, DYNLRB2, KLHL10, RIMBP3C, SEPT12, TIMD4, TSACC and TTC25) were common between MArrest and teratospermia, and three genes among 435 genes (0.007%) (HRASLS, LIMS3 and MRPL42) were common between oligospermia and teratospermia." (PMID 29150651, 2017).
TSACC also shares sentences with these, for which no sentence is quoted: cancer (1 paper); teratospermia (1).